CDKN2A (cyclin dependent kinase inhibitor 2A)
Diseases named in the same sentence as CDKN2A in open-access papers (continued):
Sharing a sentence is not in itself a finding about the gene and the disease.
osteosarcoma (continued). "Using a comparison of infused normal MSCs, in vitro spontaneously transformed MSCs, and osteosarcoma murine cells, Mohseny and co-workers concluded that aneuploidy, chromosomal translocations and the homozygous loss of the Cdkn2A (p16) locus on chromosome 4 were implicated in tumour progression." (PMID 21902837, 2011). "In human patients with soft tissue sarcomas, loss of CDKN2B and CDKN2A is associated with reduced survival, while in dogs, absence or reduced levels of p16INK4A have been reported in melanoma tumours and cell lines, as well as in osteosarcoma cell lines." (PMID 19643034, 2009). "CDKN2A, which encodes the tumor suppressors p16^INK4a and p14^ARF, is often deleted or epigenetically silenced in osteosarcoma, leading to cell cycle dysregulation." (PMID 40971960, 2025). "PDHA1 and CDKN2A were obtained as specific cuproptosis-related biomarkers for osteosarcoma after artificial intelligence analysis." (PMID 36967449, 2023). "And relative to CDKN2A, its expression was significantly higher in osteosarcoma than in paraneoplastic tissues." (PMID 36967449, 2023). "The variants in NF1 and CDKN2A, found in a patient with MPNST and a patient with osteosarcoma respectively, were detected in the germline, thus confirming the diagnosis of a cancer predisposition syndrome." (PMID 36805510, 2023). "As PTEN and CDKN2A (which codes for p16INK4A) are among the most frequently downregulated or deleted loci in osteosarcomas, the protein expression of both was assessed by Western blot." (PMID 38201229, 2023). "In the current study, we investigate the role of the Cdkn2a/Cdkn2b genes in the spontaneous transformation of murine MSCs towards osteosarcoma." (PMID 34921235, 2022). "In another study, we have demonstrated that mice injected with transformed murine MSCs, all with loss of CDKN2A/CDKN2B, formed osteosarcoma, with evident osteoid formation by atypical tumour cells." (PMID 34921235, 2022). "The results showed that the expression of CDKN2A in osteosarcoma tissues was higher than that in tumor-adjacent tissues." (PMID 36263140, 2022). "Using the same murine MSC model, we have previously published that these transformed murine MSCs, including those with loss of CDKN2A/CDKN2B, show hallmarks of osteosarcoma with a highly complex genome and many copy number alterations." (PMID 34921235, 2022). "From MSCs to osteosarcoma, CDKN2A, ALPL, SPARC (osteonectin) and MYC were considered as origin-related factors." (PMID 34828292, 2021). "For example, HOX transcript antisense RNA (HOTAIR) inhibits cyclin dependent kinase inhibitor 2A (CDKN2A) promoter activity by DNA methylation in osteosarcoma cells." (PMID 30744670, 2019). "CDKN2A/B and MTMR7 contribute to osteosarcoma risk in our modeling studies, and IGF1 does so by proxy with size." (PMID 30890123, 2019). "The genes CDKN2A/p16/INK4A, p14/ARF, and CDKN2B/p15/INK4B are located at chromosome 9p21, and CDKN2A/p16 alteration has been implicated in osteosarcoma development." (PMID 22685381, 2012). "Using methylation-specific polymerase chain reaction (PCR), it was shown that 15/32 (47%) osteosarcomas had aberrant methylation of the p14ARF gene (CDKN2A) promoter." (PMID 21253504, 2011). "The authors showed a series of 88 human osteosarcomas that possessed similar defects in the homologous cyclin-dependent kinase inhibitor (CDKN)2A locus on chromosome 9." (PMID 21902837, 2011).
osteosarcoma (continued). "Interestingly, both studies reported a high frequency (30–41%) of individuals carrying mutations affecting the CDKN2A and CDKN2B genes previously associated with osteosarcoma risk." (PMID 37505880, 2023). "Interestingly, the chromosome 11 locus identified is located around the MTAP and CDKN2A/CDKN2B genes and overlaps with the CDKN2A/CDKN2B locus, which is associated with osteosarcoma in other GWASs." (PMID 37505880, 2023). "Indeed, CDKN2A is deleted in 22% of osteosarcomas and CDK4 is amplified in 28% of oral melanomas, resulting in frequent cell cycle gene alteration in both tumor types." (PMID 34344882, 2021). "Thus CDKN2A/B, IGF1 and the two single candidates at their loci – MTMR7, FGF9 – seem likely to be associated with canine osteosarcoma risk." (PMID 30890123, 2019). "Moreover, they highlighted a discrepancy between CDKN2A homozygous deletions in osteosarcoma and EWS cell lines (42 and 36%, respectively) compared to primary sarcoma samples, in which the frequency of this deletion is expected to be lower." (PMID 28955656, 2017). "In contrast, the P16-coding CDKN2A locus was shown to be deleted rather than mutated in osteosarcoma samples leading to a loss of P16 expression." (PMID 25956431, 2015). "Notably, CDKN2A,MDM2, and RB1 also appeared in the PDK1-related gene signature derived from our correlation analysis, further supporting the association between PDK1 and osteosarcoma oncogenic programs." (PMID 40971960, 2025). "Our results illustrate that loss of CDKN2A and/or CDKN2B are early events in the development of osteosarcoma, and that these events can be targeted by CDK4/CDK6 inhibition, which might be used as a novel therapeutic option in approximately 20–23% of the patients." (PMID 34921235, 2022). "In particular, CNV was more frequent in CCND3, AURKB, CCNE1, GID4, and MYC in P-AYA, while MDM2, CDKN2A/B, and FRS2 were more frequently altered in adult osteosarcoma (p < 0.001)." (PMID 35705558, 2022). "The overlapping CDKN2A and CDKN2B genes and ANRIL are frequently deleted together in canine osteosarcoma." (PMID 30890123, 2019). "In a cohort of 88 osteosarcoma patients, they showed a correlation between CDKN2A/p16 protein expression and prognosis, thus linking murine MSC model to human osteosarcoma." (PMID 28955656, 2017). "This designed complex re-expressed tumor suppressor p16 (CDKN2A) and other loci in U2OS osteosarcoma cells." (PMID 22567109, 2012). "Their study explored the Cdkn2a/Cdkn2b gene locus in osteosarcomagenesis, finding that MSCs lacking p15Ink4b, p16Ink4a, or p19Arf transform faster than wild-type MSCs, suggesting that cell cycle dysregulation is key to osteosarcoma initiation." (PMID 40563473, 2025). "Some research groups have been modeling the initial benign developmental stages of osteosarcoma, in which altered MSCs lacking CDKN2A locus formed osteosarcomas in murine models." (PMID 37176108, 2023).
osteosarcoma (continued). "Experiments supported E2F-Sp1 interactions near: dihydrofolate reductase in Chinese hamster, dihydrofolate reductase in human osteosarcoma, fibroblast CTP:phosphocholine cytidylyltransferase in mouse embryo, thymidine kinase in mouse, RIP140 in human, CDKN2A, HMGA1, MYCN, and CDKN2C." (PMID 27871221, 2016). "Consistent with the mouse 45Ca osteosarcoma cell lines, cilia frequency and expression of CDK1, CCNE1 and CDC6 did not correlate with CDKN2A deletion." (PMID 37845394, 2023). "For example, CDKN2A is deleted in 22% of canines but only altered in 5% of human pediatric osteosarcomas, while RB1 is altered in 16% of human pediatric osteosarcomas but none of the canine tumors." (PMID 34344882, 2021).
head and neck squamous cell carcinoma (79 papers, 2004 to 2025). A squamous cell carcinoma that arises from any of the following anatomic sites: lip and oral cavity, nasal cavity, paranasal sinuses, pharynx, larynx, and salivary glands. "The comprehensive genomic analysis of the head and neck squamous cell carcinoma (HNSCC) oncogenome revealed the frequent loss of p16INK4A (CDKN2A) and amplification of cyclin D1 genes in most human papillomavirus–negative HNSCC lesions." (PMID 38954773, 2024). "CDKN2A gene is frequently mutated in head and neck squamous cell carcinomas." (PMID 29504908, 2018). "The cuproptosis-related gene CDKN2A is associated with the malignant behavior of head and neck squamous cell carcinoma (HNSCC), and plicamycin inhibits the progression of HNSCC, indicating its potential as a cuproptosis inducer." (PMID 38662225, 2024). "This study aimed to identify potential biomarkers in patients with recurrent or metastatic head and neck squamous cell carcinoma (HNSCC) and further probe the prognostic implications of CDKN2A mutations, particularly within a subset receiving immunotherapy." (PMID 37936609, 2023). "Furthermore, CDKN2A displayed higher mutation frequency in head and neck squamous cell carcinoma (104%), lung squamous cell carcinoma (73%), skin cutaneous melanoma (61%), pancreatic adenocarcinoma (36%), bladder urothelial carcinoma (27%), and lung adenocarcinoma (24%)." (PMID 37534256, 2023). "Mutations in the CDKN2A gene are found in approximately 25% of head and neck squamous cell carcinomas (HNSCC)." (PMID 26057471, 2015). "We used several analytical modules in HPVTIMER to briefly explore the role of CDKN2A in head and neck squamous cell carcinomas." (PMID 38867938, 2023). "Targeting six immune-related genes (CXCL5, ADM, FGF9, AIMP1, STC1, and CDKN2A) in individuals diagnosed with head and neck squamous cell carcinoma has shown promising results in immunotherapy triggered by periodontal disease." (PMID 37675228, 2023). "Increased risk of head and neck squamous cell carcinoma (HNSCC), particularly oral squamous cell carcinoma (OSCC) in those with germline CDKN2A mutations, has been described." (PMID 35123577, 2022). "Deletion of CDKN2A is associated with a poor prognosis in soft tissue sarcomas and is an independent prognostic factor in HPV-negative head and neck squamous cell carcinomas." (PMID 35311137, 2022). "CDKN2A hypermethylation correlates with tumor progression, metastasis, and overall survival, thus representing a promising diagnostic and prognostic biomarker in HNSCC (head and neck squamous cell carcinoma)." (PMID 32806509, 2020). "In turn, CHK1 inhibitor Prexasertib is effective against human head and neck squamous cell carcinoma cell lines with CDKN2A genetic losses." (PMID 33167404, 2020). "Demographic and clinicopathologic characteristics of all HPV-negative head and neck squamous cell carcinomas stratified by CDKN2A copy number." (PMID 29670856, 2018). "Immunohistochemical detection of p16INK4A overexpression, a product of tumor suppressor gene CDKN2A, has been associated with HPV-related head and neck squamous cell carcinoma and in some studies used as a surrogate biomarker for HPV detection." (PMID 21789265, 2011).
head and neck squamous cell carcinoma (continued). "Higher than expected frequencies of other types of cancers, such as head and neck squamous cell carcinoma (HNSCC), neural system tumors, GI cancer, breast cancer, and lung adenocarcinoma are reported in association with CDKN2A mutations, depending on the protein (either p14 or p16) affected." (PMID 35123577, 2022). "We apply SigFuge to RNA-seq cohorts of 177 lung and 279 head and neck squamous cell carcinoma samples from the Cancer Genome Atlas, and identify several cases of differential isoform usage including CDKN2A, a tumor suppressor gene known to be inactivated in a majority of lung squamous cell tumors." (PMID 25030904, 2014). "This study aims to enhance the prognosis prediction of Head and Neck Squamous Cell Carcinoma (HNSCC) by employing artificial intelligence (AI) to analyse CDKN2A gene expression from pathology images, directly correlating with patient outcomes." (PMID 38751024, 2024). "The present study aims to identify the microRNAs targeting CDKN2A gene transcripts and demonstrate their prognostic significance in head and neck squamous cell carcinoma (HNSCC)." (PMID 38164368, 2024). "Other causes include inherited gene defects in particular involving the CDKN2A locus and leading to the development of head and neck squamous cell carcinomas (HNSCC)." (PMID 34199373, 2021). "Folate deficiency is associated with hypermethylation of the p16INK4A (CDKN2A) gene in human head and neck squamous cell carcinoma (HNSCC) and a rat model of hepatocellular carcinoma." (PMID 17805414, 2007). "The cuproptosis-related gene Cyclin-dependent kinase inhibitor 2A (CDKN2A) is linked to the malignancy of head and neck squamous cell carcinoma (HNSCC), with plicamycin showing strong binding to CDKN2A and inhibiting HNSCC progression, indicating its role as a cuproptosis inducer." (PMID 38693584, 2024). "CDKN2A mutations that prevent its binding to CDKs can lead to uncontrolled growth in various tumors, including NSCLC, PAAD, head and neck squamous cell carcinoma (HNSCC), and breast and ovarian cancers." (PMID 38918694, 2024). "For example, a study developed a prognostic model based on four cellular senescence-related genes (BAK1, DKK1, CDKN2A, and MIF) to predict the survival rate of individuals with head and neck squamous cell carcinoma." (PMID 37580647, 2023). "Furthermore, mRNA expression of the CDKN2A in HNSCC (head and neck squamous cell carcinoma) was upregulated compared with normal tissues in the GEPIA (Gene Expression Profiling Interactive Analysis) database (p-Value < 0.01)." (PMID 36551770, 2022). "Disrupted Rb pathway (loss of expression of RB1 and/or of CDKN2A) in 55.9% of analysed cases confirmed the hypothesis that RB1 pathway is altered in head and neck squamous cell carcinomas, with CDKN2A (45%), rather than RB1 (11.8%) being more frequently inactivated." (PMID 15083191, 2004).
head and neck squamous cell carcinoma (continued). "Human papillomavirus-negative (HPV−) head and neck squamous cell carcinoma (HNSCC) develops through multiple mutations in key tumor suppressor genes, most notably CDKN2A." (PMID 40940964, 2025). "On the other hand, decreased expression of CDKN2A might play an important role in head and neck squamous cell carcinoma (HNSCC) that present with negative HPV results." (PMID 33896386, 2021). "Moreover, deletion of the CDKN2A locus together with functional inactivation of the tumor suppressor protein p16INK4A have been detected in head and neck squamous cell carcinoma without a relationship with HPV infection." (PMID 21789265, 2011).